OR4P4 (olfactory receptor family 4 subfamily P member 4)
Description:
Odorant receptor.
Synonyms: OR4P3P
Tractability: Antibody: UniProt places it where antibodies can reach, with medium confidence; UniProt predicts a signal peptide or a membrane-spanning region; its Gene Ontology location is reachable by antibodies, with medium confidence.
Gene: Protein-coding gene on chromosome 11 (55,635,113 to 55,640,309, forward strand). Ensembl gene ENSG00000181927.
Subcellular location: Cell membrane
Pathways (Reactome):
Sensory Perception: Expression and translocation of olfactory receptors
Gene Ontology:
Molecular function: olfactory receptor activity; G protein-coupled receptor activity
Biological process: detection of chemical stimulus involved in sensory perception of smell; G protein-coupled receptor signaling pathway
Cellular component: plasma membrane; membrane
Genetic constraint (gnomAD): Loss-of-function variants: 0 observed, 0.54 expected, observed/expected ratio (o/e) 0, 90% interval 0 to 1.83. That is too few expected variants to judge how well the gene tolerates losing a copy. Missense variants: 260 observed, 273.2 expected, observed/expected ratio (o/e) 0.95, 90% interval 0.86 to 1.05. Synonymous variants: 89 observed, 94.9 expected, observed/expected ratio (o/e) 0.94, 90% interval 0.79 to 1.12.
Homologues: Orthologues: mouse Or4p4 (86% identical), rat Or4p4 (84% identical), dog OR4P4 (84% identical), rabbit OR4P4 (84% identical). Paralogues in human: OR4S2 (60% identical), OR4C3 (52% identical), OR4C12 (52% identical), OR4C15 (52% identical), OR4A5 (51% identical), OR4S1 (51% identical), OR4X2 (51% identical), OR4A15 (51% identical), OR4C11 (51% identical), OR4A47 (50% identical), OR4B1 (50% identical), OR4C13 (50% identical), and 116 more.
Diseases named in the same sentence as OR4P4 in open-access papers:
OR4P4 is named in the same sentence as 5 diseases in open-access papers, as found by Europe PMC text mining. Sharing a sentence is not in itself a finding about the gene and the disease. The quoted sentences say what the papers report.
Obesity (5 papers, 2013 to 2025). Accumulation of substantial excess body fat. "The regions showing association with obesity‐related phenotypes are located at 11q11 (OR4P4, OR4S2, OR4C6), 1p21.1 (AMΥ1), 10q11.22 (NPY4R), 10q26.3 (CYP2E1), 16q12.2 (FTO), 16p12.3 (GPRC5b), and 4q25 and have been associated with adult obesity as well." (PMID 41082226, 2025). "Interestingly, a common copy number variant region was identified on chromosome 11q11 associated with obesity and exclusively covering three OR genes, OR4p4, OR4S2 and OR4C6." (PMID 25943692, 2015). "In a genome-wide association study (GWAS), variants of three olfactory genes, OR4P4, OR4S2 and OR4C6, were found to be associated with obesity." (PMID 38248819, 2023). "The block contains a copy number deletion involving OR4P4, OR4S2, and OR4C6 genes which is associated with early extreme obesity in previous studies using genotyping arrays and suggesting the link between olfactory dysfunction and obesity." (PMID 38110883, 2023). "It is worth mentioning that a recent genome-wide large study has associated the deletion of a region exclusively covering three out of six of these loci, OR4P4, OR4S2, and OR4C6 with early-onset (extreme) obesity." (PMID 23503716, 2013).
breast carcinoma (3 papers, 2017 to 2021). "A genome-wide analysis of CNVs identified deletions at the OR4C11/OR4P4 locus that were also associated with breast cancer risk." (PMID 28302160, 2017). "Association tests of CNVs, followed by experimental validation of CNV calls, found deletions overlapping the OR4C11 and OR4P4 genes were associated with breast cancer (P = 0.02 and P = 0.03, respectively)." (PMID 28302160, 2017). "A genome-wide association study of the cases and controls identified deletions overlapping three gene regions (DOCK5, 6.9-fold, P = 0.003; OR4C11, 2.6-fold, P = 0.02, and OR4P4, 2.4-fold, P = 0.03) that were associated with an increased risk of breast cancer after accounting for multiple testing." (PMID 28302160, 2017). "Indeed, this patient harbored several CNVs reported as associated with breast cancer risk involving UGT2B17, OR4C11, OR4P4, OR4S2 and GSTT1 genes." (PMID 33503040, 2021). "Moreover, other common CNVs were found to be associated with breast cancer risk through whole genome CNV genotyping studies including those disrupting OR4C11, OR4P4, OR4S2 and UGT2B17 genes." (PMID 33503040, 2021). "We have replicated CNVs (n = 5) from the familial breast cancer study, including CNVs in genes ANKS1B19, OR4C11, OR4P4, UGT2B17, OR4C6, OR4S215." (PMID 29116104, 2017). "Deletions in three genes were associated with increased risk of breast cancer (DOCK5, P = 3 × 10-3; OR4C11, P = 2 × 10-2; and OR4P4, P = 3 × 10-2). qPCR did not confirm the small 646-base-pair deletion at the DOCK5 locus." (PMID 28302160, 2017).
tumor (1 paper, 2024). "Of note, from RCC42, three deep deletions, UGT2B17, OR4P4 and CES1P1 were consistently observed in both parental tumor and organoid lines." (PMID 38923304, 2024).
OR4P4 also shares sentences with these, for which no sentence is quoted: breast tumour (1 paper); cancer (1).